NRP2 (neuropilin 2)
Diseases named in the same sentence as NRP2 in open-access papers (continued):
Sharing a sentence is not in itself a finding about the gene and the disease.
tumor (continued). "Together with plexins (plexin-A1) and neuropilins (Nrp-1 and Nrp-2), semaphorins (including SEMA3A) have the ability to interrupt vascular formation and tumor vascularization." (PMID 30971898, 2019). "In this study, we have compared the various tumor-inhibitory effects following transient RNAi-mediated depletion of NRP1, NRP2 or GIPC1 either alone or in combination, in PDAC cell lines with different expression levels." (PMID 31664117, 2019). "In this study, we directly compare the various tumor-inhibitory effects of transient RNAi-mediated depletion of NRP1, NRP2 and GIPC1, alone or in combination, in a set of cell lines with different expression levels." (PMID 31664117, 2019). "However, it remains unknown how the generation and secretion of SDF1/CXCR4 molecules correlate in the same cancer cell and how they interact with upstream and downstream pathways, e.g., AnnexinA7 and VEGFC/D-VEGFR3/NRP2 during tumor development and progression." (PMID 29783989, 2018). "We further demonstrated the anti-angiogenic capacity of quininib by examining gene expression of angiogenic factors in xenograft tumours and found that the expression of IL6, IL8, NRP2, VEGFA and FGF1 was reduced by quininib treatment." (PMID 27739445, 2016). "The correlation between the expression of SOX2 in the primary tumor and lymph node metastasization fits well with its ability to upregulate critical tumor promoting factors such as FGF2, VEGF-C and NRP2." (PMID 26540632, 2016). "Neuropilin-2 (Nrp2) is a well known receptor for the vascular endothelial growth factor-C (VEGF-C) and activates lymph nodes as well as promotes tumor metastasis by lymphangiogenesis." (PMID 27766950, 2016). "Full-length semaphorin-3C was found to be an inhibitor of tumor lymphangiogenesis and metastasis, which can induce the collapse of LEC cytoskeleton in a neuropilin-2-dependent manner and inhibit VEGF-C-induced signal transduction and LEC proliferation." (PMID 28036019, 2016). "However, no studies to date have implicated NRP2 in tumour initiation." (PMID 23436775, 2013). "Reciprocally, blocking VEGFR-3, Nrp2, or FGF-2 has been shown to inhibit tumor growth, lymphaniogensis, and metastasis." (PMID 24286034, 2013). "These tumours, in marked contrast to mouse mammary tumour virus (MMTV)-PyV-MT tumours, express abundant NRP2." (PMID 23436775, 2013). "Initially, we compared the expression of VEGF, NRP2 and BMI-1 in MMTV-GLI1 tumours with MMTV-PyMT tumours and observed dramatically higher expression of these molecules in the MMTV-GLI1 tumours." (PMID 23436775, 2013). "For this purpose, we used freshly harvested tumour cells from two MMTV-GLI1 transgenic mice and depleted NRP2 expression using shRNAs." (PMID 23436775, 2013). "The densities of VEGR1 and VEGFR2 were varied from 0 to 10,000 receptors/tumor cell, and the densities of NRP1 and NRP2 were varied from 0 to 100,000 receptors/tumor cell." (PMID 22104283, 2011). "In this regard, a recent study has documented the ability of fucoidans to inhibit VEGF-induced angiogenesis and tumor neovascularization in vivo, likely through modulation of cell surface neuropilins (NRP1 or NRP2) and other VEGF receptors." (PMID 21387013, 2011). "Neuropilin-1 and NRP2 are present in various tumour types from patient specimens and overexpressed NRP1 or both NRPs correlate with tumour growth, disease progression, and patient prognosis." (PMID 20087344, 2010). "With these limitations, we observed that class-3 semaphorins (A–G) and their receptors NRP1/NRP2 as well as SEMA4D and VEGF expressions were heterogeneous between samples, which suggest a differential expression of these genes between tumours." (PMID 18781179, 2008).
tumor (continued). "NRP2 and PLTP collectively enhance ECM remodelling, facilitating tumour invasion, as PLTP could supply necessary lipids for protease activity or membrane dynamics involved in invasion." (PMID 40134439, 2025). "Neuropilin-1 (NRP-1) and neuropilin-2 (NRP-2) function as co-receptors for members of the VEGF receptor family and are proven to be involved in vascular growth, in developmental angiogenesis, and tumor-driven angiogenesis." (PMID 39507419, 2024). "In addition, cluster 25 relates to the regulation of VEGF-induced migration, including the expression of key VEGF-related genes (NRP1, NRP2, FLT1, KDR, PGF), which can promote tumour dissemination by supporting the invasion of malignant cells into the stroma." (PMID 38331751, 2024). "In addition, we detected a decrease in CENPA lactylation level and downstream genes protein level (such as YY1, CCND1 and NRP2), in 2-DG treated HCC tumor tissues." (PMID 37928273, 2023). "First, we analyzed the differences in the expression of NRPs in PAAD tumor samples and normal pancreas samples, and the results showed that both, NRP1 and NRP2, were significantly more expressed in PAAD tumor samples (p < 0.001), and 17 other cancer types had similar results." (PMID 37190154, 2023). "In contrast to tumor‐associated macrophages, we did not detect changes in IL‐10 and TGF‐β production by NRP2‐deficient AM exposed to apoptotic cells, suggesting that NRP2 does not regulate the expression of these immunosuppressive cytokines in AM." (PMID 34861108, 2022). "Compared with respective Cre-negative control tumors, only those depleted for both NRP1 and NRP2 saw a significant reduction in EDA-FN coverage around tumor vasculature, suggesting that both endothelial NRPs facilitate tumor angiogenesis by promoting vessel stability." (PMID 36970722, 2022). "NRP2 is abundantly expressed in WT tissues relative to nearby non-tumour tissues, as previously observed." (PMID 36172369, 2022). "We therefore examined whether VEGFR-2 signaling would be perturbed in tumor vasculature depleted for NRP1 and NRP2 by measuring VEGFR-2 and phosphorylated-VEGFR-2Y1175 localization to endomucin+ vessels." (PMID 36970722, 2022). "As both NRP1 and NRP2 have been reported to regulate FN fibrillogenesis in ECs in the past, we considered whether the deposition of EDA-FN around tumor vessels would be perturbed in our knockout models." (PMID 36970722, 2022). "Furthermore, NRP2 co-immunoprecipitated with PTEN, a pro-tumor protein, required by SEMA 3F for the inhibition of mTOR and PI3K pathway." (PMID 34277411, 2021). "In this study, NRP2 inhibition, in a pancreatic cancer model, results in delayed clearance of apoptotic cells, and lead to increased LT CD8+ and NK cell infiltration within the tumor, consequently decreased in tumor growth." (PMID 34277411, 2021). "Therefore, we tested the 1E9 antibodies on ccRCC (A498 and 786-O, high expression of Neuropilin 1 and Neuropilin 2) and breast (MDA-MB-231, high expression of Neuropilin 1 positive and low expression of Neuropilin 2) tumor cells." (PMID 34067671, 2021). "Some studies also attest that NRP2 contributes to CSC function and tumor formation." (PMID 34277411, 2021). "RMRP might serve as a tumor promoter to accelerate cell proliferation, migration, and invasion of ESCC through regulating the miR-613/NRP2 axis." (PMID 34516335, 2021). "Some of the most well-studied lymphangiogenic factors that govern tumor lymphangiogenesis are the vascular endothelial growth factor (VEGF-C/D and VEGFR-2/3), neuroplilin-2 (NRP2), fibroblast growth factor (FGF), and hepatocyte growth factor (HGF), to name a few." (PMID 33172072, 2020). "Our findings revealed a novel mechanism whereby NRP2 induced PNET angiogenesis via dephosphorylation of cofilin at Ser-3, suggesting that NRP2 antagonism may prevent angiogenesis and tumor growth in PNETs." (PMID 32983407, 2020).
tumor (continued). "While the tumor inhibition following only NRP2 knockdown was observed as before, there was no synergistic or additive inhibition of tumor growth in the combination groups." (PMID 31664117, 2019). "However, 2 of the tumor patient serum samples (30# and 31#) showed significantly higher concentrations of NRP1 and NRP2 than those of normal human serum." (PMID 30758083, 2019). "In vitro experimental evidence indicated that the inhibition of aberrant angiogenesis elicited by local or systemic administration of Sema3F in vivo may be mediated by the NRP2-dependent inhibition of VEGF production and Akt-mTOR signaling in tumor cells." (PMID 31052281, 2019). "The seven class 3 semaphorins, SEMA3A-G, are secreted members of a large family of guidance factors that regulate processes, such as developmental and tumor angiogenesis, by signaling through receptors composed of NRP1 or NRP2 and plexinA or plexinD, respectively." (PMID 30717262, 2019). "The concentrations of Nrp1 and Nrp2 in 43 of the tumor patient samples were within the ranges of those found in normal human serum." (PMID 30758083, 2019). "Likewise, the regulators of cell differentiation and proliferation, VEGFA, DLG4, CDK, NRP2 and ACHE, were also found to be down-regulated in the mtDNA-depleted tumours but presented higher levels of expression in the cells." (PMID 30208958, 2018). "Defining the impact of the tumour microenvironment on this molecular process and identifying the entire repertoire of signalling pathways activating GLI1 will be crucial for the success of future anti-NRP2 therapies." (PMID 23505092, 2013). "Thus, differences in expression of NRP1 and NRP2 measured by microarray can be assumed to be primarily due to endothelial cells, and differences in PLXNB1 due to tumor cells." (PMID 23667446, 2013). "Indeed, an antibody binding the VEGF bindings of Nrp2 (anti-NRP2B) has been developed, and found to inhibit tumour lymphatic development and prevent metastasis." (PMID 22948112, 2012). "Concurrent inhibition of Nrp2 and IGF-1R prevented tumor growth in vivo." (PMID 22948112, 2012). "NRP-2 is also known to bind to VEGF and participate in tumor angiogenesis and growth." (PMID 23185562, 2012). "Therefore, accurate estimates of neuropilin expression and the relative density of NRP1 compared to NRP2 are required, as the response to anti-VEGF therapy is sensitive to this property of the tumor microenvironment." (PMID 22104283, 2011). "The current model includes NRP1 on muscle cells, and both NRP1 and NRP2 on tumor cells, which have not appeared in previous models." (PMID 22104283, 2011). "Western blotting experiments showed that HT29ctrl and HT29NRP2 express the same level of semaphorin 3F, whereas no semaphorin 3F was found in Colo320 cells, suggesting that NRP2-mediated tumor proliferation does not involve semaphorin 3F." (PMID 21747928, 2011). "Knockdown of NRP-2 did not affect the proliferation of the CNDT 2.5 cells in vitro; however, loss of NRP-2 reduced the growth of tumor xenografts in vivo." (PMID 22028766, 2011). "Receptors for VEGF (e.g., VEGFR1, VEGF2, Nrp1, Nrp2) are expressed on multiple cancer cell lines, and there is evidence that VEGF can function as a cell survival factor for tumor cells and vascular endothelial cells within the tumor." (PMID 20628530, 2010). "Furthermore, NRP2 siRNA also decreased tumour cell migration, and combined transfection with NRP1 and NRP2 siRNAs had a greater effect." (PMID 20087344, 2010). "In these tumours, SEMA3B, SEMA3G and NRP2 expressions were related to prolonged survival." (PMID 18781179, 2008). "However, the potential functions and mechanisms of NRP1 and its homologous isoform, NRP2, in tumor progression and tumor immunology have not been fully elucidated." (PMID 37190154, 2023).
tumor (continued). "Furthermore, inhibiting NRP-2 in vivo decreased PNET angiogenesis and tumor development." (PMID 35052853, 2022). "In addition to tumor tissues, we also subjected Moc2 EphB4 KO and control cell lines to RNA-seq analysis and observed similar changes in the genes involved in the VEGF signaling pathway including VEGFA, DLL1, NRP2." (PMID 35725568, 2022). "This phenomenon may occur in TAMs, with NRP2-expressing cells residing within an inhospitable TME and NRP1 expressing TAMs located in regions with supportive conditions or having more recently emigrated to the tumor." (PMID 35651620, 2022). "In contrast, PLXNA1 showed higher expression in C1, C2 and C6, NRP2 and PLXNC1 had increased expression in C6, indicating that these genes may mainly play a tumor promoter role as patients characterized into those subtypes had worse survival due to higher proliferation rate and enrichment of TGFβ." (PMID 32640719, 2020). "Furthermore, blocking NRP2 in vivo suppressed PNET angiogenesis and tumor growth." (PMID 32983407, 2020). "Therefore, it is reasonable to suppose that AnnexinA7 through the coordination of VEGFC/D-VEGFR3/NRP2, and SDF1/CXCR4 may affect the process of tumor development and progression." (PMID 29783989, 2018). "However, there is still no direct evidence that blocking NRP2 in OS results in decreased blood vessel formation, tumor growth, or metastatic potential." (PMID 25890345, 2015). "Over the past two decades, many key factors have been identified as important regulators for tumor lymphangiogenesis, but the major focus in anti-lymphangiogenic therapy has been targeting through VEGF-C and -D, and their membrane receptor VEGF-R3 and coreceptor (Nrp-2)." (PMID 22481918, 2012). "The discrepancy between in vitro and in vivo growth inhibition may be due to NRP-2-mediated responses from cells in the tumor microenvironment at the tumor site in vivo that are not appreciable in an in vitro system." (PMID 22028766, 2011). "To examine the effect of NRP-2 knockdown on the growth of gastrointestinal cancer cells in vivo, we injected CNDT 2.5 shcntr or shNRP-2 clones in the livers (a common site for gastrointestinal cancer metastasis) of mice (10 animals per group) and assessed tumor incidence and tumor volume." (PMID 22028766, 2011). "We tested the hypothesis that tumour-derived VEGF-C may play an autocrine role in metastasis by promoting cellular motility through one or more VEGF-C-binding receptors VEGFR-2, VEGFR-3, neuropilin (NRP)-1, NRP-2, and integrin α9β1." (PMID 17912247, 2007). "Interestingly, no other significant correlations between NRP2 expression and e.g., tumor staging or vessel invasion could be found which might be due to limitations in the immunohistochemical analysis of tissue arrays." (PMID 26573807, 2015). "We expand upon this knowledge by demonstrating that tumor-associated distal lymphatics downstream of SLNs undergo functional and structural remodeling during disease progression, which can be mitigated via treatment with function blocking antibodies to VEGF-C or NRP2, but not VEGF-A." (PMID 23874750, 2013). "This infers that VEGFR2, but neither by NRP2 nor VEGFR3, relayed the negative control of VEGFC on tumor." (PMID 33067561, 2020). "In conclusion, our findings show that the activity of endothelial NRPs together is required for sustained tumor angiogenesis, and support a hypothesis that maximum antiangiogenic efficacy can be achieved by cotargeting both NRP1 and NRP2 rather than targeting either receptor individually." (PMID 36970722, 2022).
cancer (85 papers, 2008 to 2026). A tumor composed of atypical neoplastic, often pleomorphic cells that invade other tissues. "NRP1 and NRP2 have already been implicated in cancer invasion, metastasis and progression, but this is not the case for SEMA3F, which has been traditionally considered a good prognostic marker not only for BC but also for several other types of cancer." (PMID 39138514, 2024). "In conjunction, loss of Nrp2 by cancer cells increased VEGF levels in culture, resulting in VEGFR2 phosphorylation and activation of downstream signaling by MAPKs to promote endothelial cell migration and sprouting." (PMID 38592275, 2024). "Nrp2 expression is inversely associated with EGFR expression in cancer cells and inhibits the rescue pathways within EGFR- or MET-addicted carcinoma cells, likely through NF-κβ repression." (PMID 38592275, 2024). "Nrp2 expression is also associated with decreased IGF-IR in PTENNull tumors, and Nrp2 ablation in cancer cells restored the efficacy of IGF-IR-targeted therapy." (PMID 38592275, 2024). "Angiogenesis can promote the growth of cancer cells, while both NRP2 and PLXNB1 have been verified to be vascular-associated genes." (PMID 36460803, 2023). "Nrp2-knockout (Nrp2−/−) mesenchymal-like CRC organoids were employed in vitro 3D and in vivo subcutaneous tumorigenesis models to explore the mechanisms underlying the cancer cell-intrinsic pro-tumorigenic effects of Nrp2." (PMID 35158941, 2022). "In fact, NRP2 is frequently overexpressed in tumors and is associated with a poor prognosis in various cancers." (PMID 33918816, 2021). "To date, insufficient data are available on NRP2 transcript-specific associations with histopathological parameters and cancer prognosis." (PMID 33918816, 2021). "High NRP2 expression has been associated with increased motility and invasiveness in cancer cell models." (PMID 34239847, 2021). "Previous studies have reported that NRP2 is associated with cancer metastasis, and we also found that NRP2 was considerably increased in suspension cells." (PMID 33396906, 2020). "NRP2 has been implicated in metastatic progression, although it usually occurs in carcinomas just in small amounts." (PMID 30717262, 2019). "NRP2 expression was associated with an increased risk of an early cancer specific death among these patients supporting its role as a promoter of therapy resistance." (PMID 27026195, 2016). "By using sc-RNAseq, this paper highlights the inter- and intra-tumoural heterogeneity of NRP1 and NRP2 expressions across different cell types in different cancer types, namely ccRCC and SKCM where each of the isoforms were distinctively highest." (PMID 40134439, 2025). "The nuanced roles of neuropilin (NRP) isoforms, NRP1 and NRP2, have attracted considerable scientific interest regarding cancer progression." (PMID 40134439, 2025). "The functional divergence between NRP1+ and NRP2+ TAMs reflects the cancer type-specific heterogeneity and highlights their specialized roles in modulating the TME." (PMID 40134439, 2025). "Conversely, the add-back of NRP2 to CAF-200 cells restored their capacity to promote cancer cell invasion and migration, and NRP2 overexpression enhanced the ability of LFs to promote cancer cell invasion and migration." (PMID 38766528, 2024). "Cancer cells with high levels of both Nrp2 and α6β1 integrin form more focal adhesions with laminin, and that adhesive strength on laminin is Nrp2-dependent." (PMID 38592275, 2024). "Nrp2 codes for a transmembrane protein that contributes to a number of signaling pathways that contribute to the cytoskeleton, angiogenesis, and cancer progression." (PMID 39180406, 2024). "Numerous preclinical studies have demonstrated the efficacy of Nrp2 inhibition for the treatment of cancers." (PMID 38592275, 2024). "Although our study identified the roles of PTN and VEGF-D in the interplay between CAFs and cancer cells, further investigation is warranted to explore the crosstalk between NRP2 and these proteins." (PMID 38766528, 2024).